TFAP4 (transcription factor AP-4)
Diseases named in the same sentence as TFAP4 in open-access papers (continued):
Sharing a sentence is not in itself a finding about the gene and the disease.
tumor (16 papers, 2016 to 2025). "The results of the present study can help to understand vital parts of TFAP4 in the context of tumours, reveal the possible association of TFAP4 with tumour‐immune interactions and illustrate the potential mechanism." (PMID 33373169, 2021). "Meanwhile, tumor sizes, the presence of vascular invasion, and TFAP4 expression were found to be risk factors that independently affect DFS." (PMID 31281549, 2019). "However, TFAP4-deficient tumor cells displayed increased spontaneous DNA damage, chromosomal instability (CIN), and cellular senescence mediated by direct or indirect MiR-22-3p repression by AP4." (PMID 36891298, 2023). "Additionally, the associations between TFAP4 and the levels of tumour infiltration, tumour mutational burden (TMB) and microsatellite instability (MSI) were analysed for different types of tumour using correlation analysis." (PMID 33373169, 2021). "Knockdown of TFAP4 slows tumor growth and promotes tumor differentiation in a mouse xenograft model of MNA-NB." (PMID 41244073, 2025). "Another study employed nonviral ModPoKI screening, which is combinatorial KI of BATF and TFAP4, and demonstrated effective tumor control against Nalm-6 leukemia with GD2 expression." (PMID 40693464, 2025). "In particular, CAR-T cells with combined BATF and TFAP4 KI exhibited superior tumor control compared with single KIs, showing a reduction of terminally differentiated Tem cells but increased Tscm and Tcm cells." (PMID 40693464, 2025). "Apart from its oncogenic functions in malignant cells, TFAP4 promotes tumor angiogenesis by blocking the inhibitory effect of CCL23115." (PMID 40155749, 2025). "TFAP4 presumably maintains tumor hallmarks by repressing or activating genes that contain CAGCTG elements in their promoter regions, thereby regulating biological processes such as proliferation, epithelial-mesenchymal transition (EMT), and metabolism." (PMID 36891298, 2023). "Of note, TFAP4, a downstream target of some miRNAs, is negatively modulated by miRNAs, thereby participating in tumor suppression." (PMID 34983307, 2022). "Collectively, miR-373-3p functions as an anti-tumor gene in HCC by inhibiting TFAP4/PI3K/AKT pathway." (PMID 34983307, 2022). "miR-373-3p negatively modulated TFAP4, and TFAP4 overexpression inverted miR-373-3p-mediated anti-tumor effects." (PMID 34983307, 2022). "More importantly, the TFAP4 level was also significantly related to the degree of tumour infiltration." (PMID 33373169, 2021). "TFAP4 is a direct transcriptional target of certain miRNAs and participates in the tumor progression of diverse tumors." (PMID 34141611, 2021). "Taken together, we suggest that sh-TTN-AS1-1 exerts its anti-tumor role through mediating miR-16-1-3p/TFAP4 axis in OS." (PMID 34141611, 2021). "Encouragingly, the feedback experiments showed that up-regulation of TFAP4 mitigated the anti-tumor function of sh-TTN-AS1-1 in OS cells." (PMID 34141611, 2021). "TFAP4 overexpression or miR-16-1-3p silencing visibly reversed the inhibitory effect of sh-TTN-AS1-1 on tumor progression of MG63 cells (P < 0.01)." (PMID 34141611, 2021). "TFAP4 expression was considerably enhanced in tumor tissues of OS patients (P < 0.001), and was inversely correlated with miR-16-1-3p expression in OS tissues (r = -0.3689, P = 0.0029)." (PMID 34141611, 2021). "In summary, our study revealed that in the Han Chinese population of Qingdao city and the surrounding regions, miR-608 was downregulated, while TFAP4 was upregulated in the tumor tissues of patients with NSCLC." (PMID 31552102, 2019). "Upregulated TFAP4 expressions were discovered in HCC cell lines compared to the healthy liver cell line, and similarly, the levels of TFAP4 were higher in tumor tissues than its expression in paratumor tissues." (PMID 31281549, 2019). "Analysis of 10 human fresh HCC samples using qRT-PCR and western blot revealed that tumor tissues possessed higher TFAP4 mRNA and protein expression levels compared to paratumor tissues." (PMID 31281549, 2019).
tumor (continued). "In conclusion, we have showed that TFAP4 is a valuable prognostic biomarker in determining the likelihood of tumor metastasis and recurrence, as well as the long-term survival rates of HCC patients." (PMID 31281549, 2019). "In conclusion, our study demonstrated that TFAP4 is a valuable prognostic biomarker in determining the likelihood of tumor metastasis and recurrence, as well as the long-term survival rates of HCC patients." (PMID 31281549, 2019). "Cox proportional hazards regression revealed tumor sizes, TNM stage, and TFAP4 expression to be risk factors that independently determine OS rates." (PMID 31281549, 2019). "We identified that the expression of TFAP4 mRNA in 369 tumor tissues was higher than that in 160 normal liver tissues." (PMID 31281549, 2019). "We also observed significantly reduced tumor growth in the TFAP4-silenced group (+ Dox) compared with the control (− Dox), from day 31 onwards." (PMID 29880876, 2018). "Our data also revealed the upregulation of TFAP4/AP4 (transcription factor AP-4) in eBL tumor cells." (PMID 29132323, 2017). "Overall this study suggests a regulatory circuit in which MYCN by elevating TFAP4 expression, cooperates with it to control a specific set of genes involved in tumor progression." (PMID 27448979, 2016). "TFAP4 was correlated using gene markers in tumour‐infiltrating immune cells and immune scores." (PMID 33373169, 2021). "Moreover, miR-16-1-3p inhibition or TFAP4 elevation weakened the suppressive effect of TTN-AS1 silencing on OS cell tumor progression." (PMID 34141611, 2021). "However, there are few reports on TFAP4 and tumor cell apoptosis; thus, the present study aimed to investigate the potential relationship between TFAP4 and apoptosis." (PMID 31552102, 2019). "However, they only analyzed a small sample size of case data from one medical center and only studied the role of TFAP4 in promoting tumor formation and proliferation of HCC cells." (PMID 31281549, 2019). "TFAP4 staining was primarily observed in the nuclei of tumor cells." (PMID 31281549, 2019). "Therefore, we guessed that miR-373-3p functioned as an anti-tumor gene in HCC by targeting TFAP4." (PMID 34983307, 2022). "To assess the levels of gene expression for all tumour stages, we compared TFAP4 expression in patients with stage I, II, III or IV tumours." (PMID 33373169, 2021). "Moreover, TFAP4 KI of CAR-T cells promoted T cell killing capacity upon repeated antigen stimulation and improved tumor control in a murine leukemia model." (PMID 40693464, 2025). "Despite this, the lack of phenotype observed with T21RBCC-VHHGFP highlights that TFAP4 does not affect tumour growth." (PMID 37925433, 2023). "HIF1A-As2 KD by ASO significant repressed MYC, and mesenchymal markers TFAP4 and SNAIL in tumor." (PMID 37041291, 2023). "Decreased TFAP4 expression in + Dox tumors was verified by western blot, indicating that tumor progression was not due to escape from silencing of TFAP4." (PMID 29880876, 2018). "Generally, TFAP4 expression was up‐regulated in advanced tumours in ESCA, KIRC, KIRP,LIHC, LUAD, TGCT and THCA, while it was down‐regulated in advanced tumours in BLCA, BRCA, KICH, LUSC,MESO and SKCM, and was stable in advanced tumours in ACC, CHOL, COAD, HNSC, PAAD, READ, STAD and UVM." (PMID 33373169, 2021).
gastrointestinal tumors (1 paper, 2016). "Despite multiple reports correlating TFAP4 expression and malignancy in gastrointestinal tumors, TFAP4 has not been previously implicated as a regulator of canonical WNT signaling." (PMID 27996937, 2016).
heart disease (1 paper, 2025). "Using snRNA-seq analysis of human heart disease samples, we revealed that TFAP4 is expressed in diverse cardiac cell types such as cardiomyocytes and endothelial cells." (PMID 40612272, 2025).
TFAP4 also shares sentences with these, for which no sentence is quoted: prostate carcinoma (2 papers); B cell lymphomas (1); bladder cancer (1); blood cancers (1); pancreatic adenocarcinoma (1); small cell lung carcinoma (1).